CYTL1 (cytokine like 1)
Synonyms: C4orf4; C17
Tractability: Antibody: UniProt places it where antibodies can reach, with high confidence; UniProt predicts a signal peptide or a membrane-spanning region; its Gene Ontology location is reachable by antibodies, with medium confidence.
Gene: Protein-coding gene on chromosome 4 (5,014,586 to 5,019,486, reverse strand). Ensembl gene ENSG00000170891.
Subcellular location: Secreted
Subcellular location (Human Protein Atlas): Endoplasmic reticulum; Nuclear membrane; Predicted to be secreted
Gene Ontology:
Molecular function: signaling receptor binding
Biological process: positive regulation of transcription by RNA polymerase II; signal transduction
Cellular component: extracellular region
Genetic constraint (gnomAD): Loss-of-function variants: 18 observed, 14.57 expected, observed/expected ratio (o/e) 1.24, 90% interval 0.85 to 1.78. The upper end of that interval is the gene's LOEUF score, 1.78, which puts it in group 6 of 6, group 1 being the genes least tolerant of losing a copy. Missense variants: 213 observed, 163.9 expected, observed/expected ratio (o/e) 1.3, 90% interval 1.16 to 1.46. Synonymous variants: 91 observed, 69.88 expected, observed/expected ratio (o/e) 1.3, 90% interval 1.1 to 1.55.
Homologues: Orthologues: chimpanzee CYTL1 (99% identical), macaque CYTL1 (96% identical), pig CYTL1 (85% identical), dog CYTL1 (82% identical), guinea pig CYTL1 (77% identical), rat Cytl1 (70% identical), mouse Cytl1 (69% identical), tropical clawed frog cytl1 (46% identical), zebrafish cytl1 (28% identical).
Diseases named in the same sentence as CYTL1 in open-access papers:
CYTL1 is named in the same sentence as 29 diseases in open-access papers, as found by Europe PMC text mining. Sharing a sentence is not in itself a finding about the gene and the disease. The quoted sentences say what the papers report.
neuroblastoma (9 papers, 2016 to 2023). Neuroblastoma (NB) is the most common solid, extracranial childhood tumor. "In neuroblastoma, high expression of CYTL1 and its knockdown causes a decrease in cell proliferation and migration." (PMID 37702613, 2023). "Meanwhile, CYTL1 was also identified to be associated with the growth and metastasis of neuroblastoma cells, together with its role in vessel formation." (PMID 35898512, 2022). "Recent research indicates that Cytl1 may be associated with a number of cancers and disease pathogeneses, including neuroblastoma, alcohol dependence, and smoking-associated impaired metabolic health." (PMID 31089746, 2019). "More recently, studies have also potentially linked Cytl1 with a variety of conditions including cardiac fibrosis, smoking, alcohol dependence risk, and tumours such as benign prostatic hypertrophy, lung squamous cell carcinoma, neuroblastoma and familial colorectal cancer." (PMID 31089746, 2019). "High levels of CYTL1 expression have been seen in tumor tissues and cell lines from human neuroblastoma, and inhibiting CYTL1 prevents SH-SY5Y neuroblastoma cells from proliferating, migrating, and invading." (PMID 37745303, 2023). "High levels of CYTL1 expression were found in tumor tissues and cell lines of human neuroblastoma, and silencing CYTL1 prevented the growth, migration, and invasion of neuroblastoma cells." (PMID 37745303, 2023). "CYTL1 was found to be highly expressed in neuroblastoma and a potential therapeutic target and diagnosis biomarker." (PMID 33428606, 2021). "The role of Cytl1 as a regulatory factor was suggested by its influence on mesenchymal cell chondrogenesis and neuroblastoma cell growth, as well as its protective effects on cartilage development." (PMID 26800213, 2016). "In contrast, CYTL1 was involved in the growth and metastasis of neuroblastoma cells." (PMID 36389725, 2022). "Another report describing the effects of Cytl1 on the growth and metastasis of neuroblastoma (NB) cells revealed a possible relationship between Cylt1 expression and NB development." (PMID 26800213, 2016). "In addition, Cytl1 gene expression was detected in human tumour cell lines, particularly SH-SY5Y, and human neuroblastoma (NB) tissues, and decreased expression of the Cytl1 gene when blocked by siRNA results in reduced cell proliferation, migration and invasion activities by SH-SY5Y cells." (PMID 31089746, 2019).
breast carcinoma (6 papers, 2022 to 2025). "The baseline levels of lactate production were also negatively associated with the levels of CYTL1 expression in the three breast cancer cell lines tested." (PMID 35115484, 2022). "Although numerous studies have focused on the function of CYTL1 as a secreted protein, low levels of CYTL1 mRNA and protein are associated with breast cancer progression and metabolic reprogramming to glycolysis, inspiring us to investigate the intracellular role of CYTL1." (PMID 35115484, 2022). "A recent study reported that intracellular CYTL1 is a potential tumor suppressor that stabilizes NDUFV1 to prevent metabolic reprogramming in breast cancer." (PMID 37745303, 2023). "It has recently been shown that in breast cancer cells, CYTL1 is a tumor suppressor that keeps NDUFV1 stable and prevents metabolic reprogramming." (PMID 37745303, 2023). "CYTL1 expression was also confirmed to inhibit tumor metastasis in a breast cancer albino mouse strain BALB/cArc." (PMID 36825034, 2023). "To explore the mechanism by which CYTL1 regulates breast cancer progression, we performed transcriptome profiling using RNA-sequencing data obtained from the TCGA database." (PMID 35115484, 2022). "In breast cancer with low CYTL1 levels, cancer metabolic reprogramming is switched from OXPHOS to glycolysis." (PMID 35115484, 2022). "Accordingly, the different levels of CYTL1 protein expression were confirmed in various breast cancer cell lines and most of them showed relatively low CYTL1 expression except ZR-75-1 cells." (PMID 35115484, 2022). "The CYTL1 expression variance contributes to the variance in NDUFV1 expression in breast cancer cells." (PMID 35115484, 2022). "Here, we demonstrate that intracellular cytokine-like protein 1 (CYTL1) plays a key role in preventing the robust glycolytic switching characteristic of breast cancer." (PMID 35115484, 2022). "We also compared glucose uptake by three representative breast cancer cell lines and other six cell lines with different levels of intact CYTL1 expression." (PMID 35115484, 2022). "Because DNA copy number also has an important impact on the expression levels of the affected gene, we further analyzed CYTL1 copy number variance among breast cancer cell lines based on CCLE." (PMID 35115484, 2022). "Apart from DNA hypermethylation, active exocellular release and loss of DNA copy number may account for the low expression of CYTL1 during the malignant progression of breast cancer." (PMID 35115484, 2022). "Similar results were obtained with these three breast cancer cell lines, suggesting that CYTL1 may maintain OXPHOS status in breast cancer cells." (PMID 35115484, 2022). "It is possible that breast cancer cells might actively reduce both the mRNA and protein levels of CYTL1 to generate an intracellular environment with low CYTL1 expression." (PMID 35115484, 2022). "CYTL1 is considered a tumor suppressor in breast cancer by inhibiting metabolic reprogramming." (PMID 35898512, 2022). "Interestingly, when the methylation levels of CYTL1 in breast cancer cell lines were analyzed based on the Cancer Cell Line Encyclopedia (CCLE), no relation was detected." (PMID 35115484, 2022). "Most breast cancer cell lines harbor low CYTL1 copy numbers." (PMID 35115484, 2022). "The results indicate that CYTL1 may maintain OXPHOS status and low intracellular levels of CYTL1 in breast cancer cells are indispensable for facilitating metabolic switching toward aerobic glycolysis." (PMID 35115484, 2022). "We then evaluated the relationship between the CYTL1 protein levels and the survival rate in 80 breast cancer patients using IHC, 56 patients with lower CYTL1 expression showed a significantly poor overall survival as compared with 24 patients with higher CYTL1 level." (PMID 35115484, 2022). "Next, we investigated whether the intracellular form of CYTL1 is capable of slowing or inhibiting the growth or metastasis of breast cancer cells in vitro or in vivo by targeting glycolysis." (PMID 35115484, 2022).
breast carcinoma (continued). "Additionally, intact CYTL1 abundance positively correlated with NDUFV1 protein levels in the three breast cancer cell lines." (PMID 35115484, 2022). "Intracellular CYTL1 plays a previously unappreciated role in regulating metabolic reprogramming, dependent on NDUFV1, in breast cancer." (PMID 35115484, 2022). "In this study, we demonstrate, for the first time, that the intracellular form of CYTL1, not the extracellular form, inhibits metabolic reprogramming toward glycolysis, which has been linked to the inhibition of the cell growth and metastasis of breast cancer both in vitro and in vivo." (PMID 35115484, 2022). "During metabolic reprogramming, tumor cells reduce the intracellular level of CYTL1, which has been shown to have a negative correlation with malignant progression in patients with breast cancer." (PMID 35115484, 2022). "In the case of breast cancer, a negative correlation between malignant progression and the intracellular level of CYTL1 was observed." (PMID 35115484, 2022). "An immunohistochemical (IHC) analysis confirmed the negative correlation between CYTL1 protein expression and successive grades of breast cancer malignancy." (PMID 35115484, 2022). "Through bioinformatics analyses and experimental confirmation by using clinical samples and cell lines, the reduction of CYTL1 level and its negative relationship with clinic prognosis were uncovered in breast cancer." (PMID 35115484, 2022). "Breast cancer cells expressing an intracellular form of CYTL1 lacking a 1-22 aa signal peptide, ΔCYTL1, show significantly attenuated glucose uptake and lactate production, which is linked to the inhibition of cell growth and metastasis in vitro and in vivo." (PMID 35115484, 2022). "Different concentrations of rhCYTL1 affected neither glucose absorption nor lactate production in MDA-MB-231 cells, supporting that the intracellular form of CYTL1, not the secreted form, regulates breast cancer cell metabolism." (PMID 35115484, 2022). "Moreover, the regulator for breast cancer cell metabolism was identified to be the intracellular form rather than the secreted form of CYTL1, because ΔCYTL1 lacks the 1-22 aa signal peptide, but not rhCYTL1, affected glycolysis." (PMID 35115484, 2022). "Thus, regulating intracellular CYTL1 expression and its stabilization of the NDUFV1 protein might be a strategic approach for breast cancer therapy." (PMID 35115484, 2022).
gastric cancer (6 papers, 2022 to 2024). A primary or metastatic malignant neoplasm involving the stomach. "CYTL1 is a hub gene linked to the pathogenesis and prognostic outcomes of gastric cancer." (PMID 37124627, 2023). "As CYTL1 is hypermethylated in breast, lung and stomach cancers, its expression is significantly reduced in these cancers." (PMID 39867879, 2024). "Silencing CYTL1 facilitated intracellular ROS accumulation and suppressed migration in gastric cancer cells." (PMID 37124627, 2023). "Our further experiments demonstrated that silencing CYTL1 enabled to facilitate intracellular ROS accumulation and impair migrative capacity of gastric cancer cells, indicative of CYTL1 as a possible therapeutic target of gastric cancer." (PMID 37124627, 2023). "Among the DNA damage repair-relevant genes, the biological significance of CYTL1 in gastric cancer remains indistinct." (PMID 37124627, 2023). "This study experimentally verified the levels of DNA repair-relevant genes, with higher levels of PAPPA2, MPO, MAGEA11, DEPP1, CPZ, and COLEC12 and lower level of CYTL1 in gastric cancer cells versus controls." (PMID 37124627, 2023). "Higher levels of PAPPA2, MPO, MAGEA11, DEPP1, CPZ, and COLEC12 and lower level of CYTL1 were proven in gastric cancer cells versus controls." (PMID 37124627, 2023). "In gastric cancer, CYTL1 has also been shown to be a necroptosis-promoting oncogene." (PMID 37745303, 2023). "Furthermore, our study identified the hsa-miR-339-5p as miRNA target of CYTL1 which has previously been recognized as a suppressor of malignant development in gastric cancer thereby further cementing CYTL1 role as an oncogenic molecule in gastric cancer." (PMID 36389725, 2022). "Notably, similar to previous studies, CYTL1 functions as a prognostic factor in gastric cancer." (PMID 37702613, 2023). "CYTL1 expression was notably silenced by its specific siRNAs both in HGC-27, and MKN-28 gastric cancer cells." (PMID 37124627, 2023). "In contrast to gastric mucosa epithelial cell line GES-1, transcriptional levels of PAPPA2, MPO, MAGEA11, DEPP1, CPZ, and COLEC12 were higher in gastric cancer cell lines HGC-27, MKN-28 and AGS, with lower transcriptional level of CYTL1." (PMID 37124627, 2023). "These molecular characteristics were mainly driven by the eight NRGPI oncogenes (CYTL1, PLCL1, CNTN1, GRP, APOD, GPX3, FCN1, SERPINE1) as validated in the gastric cancer cell lines and clinical samples." (PMID 36389725, 2022).
melanoma (3 papers, 2021 to 2025). A malignant, usually aggressive tumor composed of atypical, neoplastic melanocytes. "By knocking down CYTL1 in BRAF-mutated melanoma cells, we found that CYTL1 has a negligible effect on melanoma cell proliferation but affects melanoma invasion and metastasis." (PMID 37745303, 2023). "The results showed that CYTL1 was a pro-oncogenic factor in both melanoma and BRAF-mutated melanoma, and its high expression significantly suppressed patients’ OS and DFS." (PMID 37745303, 2023). "Subsequently, we analyzed the differential expression of CYTL1 in various tumor tissues and its effect on melanoma prognosis, and resolved the mutation status of CYTL1 and its related signalling pathways." (PMID 37745303, 2023). "However, in our study, CYTL1 was a pro-oncogenic factor in melanoma, and in melanoma patients, its elevated expression was linked to a shorter OS and DFS., especially those with BRAF mutations." (PMID 37745303, 2023). "By building a protein-protein interaction (PPI) network and doing a functional enrichment analysis, we were able to pinpoint the gene CYTL1, which may be crucial to the emergence and development of melanoma with BRAF mutations." (PMID 37745303, 2023). "For instance, CYTL1 expression was progressively upregulated in normal skin, nevi or malignant nevi, and melanoma." (PMID 41574107, 2025). "Subsequently, we knocked down CYTL1 in A2058 cells to detect the effect of CYTL1 on the proliferation, migration, and invasion of melanoma cells." (PMID 37745303, 2023). "In vitro experiments further confirmed that the knockdown of CYTL1 significantly inhibited the migration and invasive ability of melanoma cells." (PMID 37745303, 2023). "Wound healing assay and transwell migration assay showed that the knockdown of CYTL1 significantly inhibited the migratory ability of melanoma." (PMID 37745303, 2023). "The results showed that CYTL1 showed a gradually increasing trend in normal skin, nevus, and melanoma." (PMID 37745303, 2023). "We analyzed CYTL1 mutations and CNA in melanoma samples from 12 databases using the cBioPortal database." (PMID 37745303, 2023). "By knocking down CYTL1 in melanoma cells, the effects of CYTL1 on melanoma cell proliferation, migration and invasion were further examined by CCK8 assay, Transwell assay and cell migration assay." (PMID 37745303, 2023). "To determine the biological function of CYTL1 in melanoma, we analyzed the differential genes in melanoma patients with high or low CYTL1 expression according to the median expression values of CYTL1." (PMID 37745303, 2023). "By analyzing the GSE46517 and GSE114445 datasets, we found that CYTL1 expression was progressively upregulated in normal skin, nevi or malignant nevi, and melanoma." (PMID 37745303, 2023). "Western blot assay and RT-qPCR experiments showed that the expression levels of CYTL1 in melanoma cells were all significantly higher than in HEM cells, among which A2058 cells had the highest CYTL1 levels." (PMID 37745303, 2023). "High levels of CYTL1 are a poor prognostic factor for melanoma patients and can also be a potential therapeutic target for BRAF-mutated melanoma." (PMID 37745303, 2023). "In melanoma patients, especially BRAF-mutated melanoma patients, clinical studies showed a positive correlation between increased CYTL1 expression and shorter overall survival (OS) and disease-free survival (DFS)." (PMID 37745303, 2023). "Among them, CYTL1 was highly expressed in melanoma, especially in BRAF-mutated melanoma, and the high expression of CYTL1 was associated with epithelial-mesenchymal transition (EMT), cell cycle, and cellular response to UV." (PMID 37745303, 2023). "Subsequently, we analyzed the OS and DFS of CYTL1 in cutaneous melanoma and BRAF-mutated melanoma." (PMID 37745303, 2023). "Considering that CYTL1 may be a potential oncogene in melanoma, it was assessed how CYTL1 interacted with PDCD1, CD274, HAVCR2, TIGIT, SIGLEC15, CTLA4, LAG3, and PDCD1LG2." (PMID 37745303, 2023).
melanoma (continued). "Knockdown of CYTL1 inhibited the migration and metastasis of melanoma." (PMID 37745303, 2023). "The results of this study support that CYTL1 may be considered a newly discovered biomarker for the diagnosis, prognosis, and treatment of melanoma." (PMID 37745303, 2023). "In conclusion, CYTL1 may be a pro-oncogenic factor in melanoma." (PMID 37745303, 2023). "These analyses showed that CYTL1 could be crucial to melanoma development." (PMID 37745303, 2023). "Therefore, we next examined whether there is a relationship between CYTL1 and immune infiltration in melanoma." (PMID 37745303, 2023). "In conclusion, CYTL1 expression is significantly upregulated in melanoma, and its upregulation can promote EMT in melanoma cells and promote melanoma progression." (PMID 37745303, 2023). "In this study, 7 genes (CYTL1, CCL8, FCGR2C, OAS1, HAPLN3, WIPF1, CLIC2) were identified as prognostic signatures for melanoma." (PMID 33428606, 2021). "Finally, we examined the expression of CYTL1 in human melanocytes HEM cells and melanoma cells A2058, A375, M14, and SK-MEL-28." (PMID 37745303, 2023).